MET (MET proto-oncogene, receptor tyrosine kinase)
Diseases named in the same sentence as MET in open-access papers (continued):
Sharing a sentence is not in itself a finding about the gene and the disease.
lung adenocarcinoma (continued). "HGF expression can induce EGFR-TKI resistance to lung adenocarcinoma cells with EGFR-activating mutations, and MET inhibition can reduce proliferation of lung adenocarcinoma cell lines that show resistance to EGFR-TKIs." (PMID 22211244, 2012). "A similar association between gefitinib resistance and HGF induced c-MET activation has also been reported for lung adenocarcinomas containing activating EGFR mutations." (PMID 21283737, 2011). "MET exon 14 splice-site mutations occur in ~3–4% of lung adenocarcinoma cases, defining a cohort of patients which might benefit from anti-MET targeted therapy." (PMID 35326531, 2022). "MET exon 14 skipping mutations occur for 1–2% of lung adenocarcinomas." (PMID 35326552, 2022). "In TCGA's cohort, nine of 230 (3.9%) lung adenocarcinomas harbored MET exon 14 skipping mutation." (PMID 27223439, 2016). "In this study, we investigated if MET gene copy number status as assessed by FISH could predict the clinical outcome for EGFR-TKI in EGFR-mutated lung adenocarcinoma patients." (PMID 25886066, 2015). "As both a positive and negative control for this analysis, we compared 10 lung adenocarcinoma samples with a MET exon 14 splice site mutation or deletion with all other lung adenocarcinoma samples to look for significant differential splicing between the two groups." (PMID 24498085, 2014). "Indeed, in EGFR/MET mice, this combination increased survival, decreased tumor burden and reduced the expression levels of all the tested key proteins implicated in lung adenocarcinoma (pEGFR, pMET, pAKT and pERK), compared with the single treatments or vehicle." (PMID 34298655, 2021). "It is previously reported that patients with lung adenocarcinoma with carcinogenic mutations at MET exon 14 RNA splice acceptor and donor sites could benefit from treatment with MET inhibitors crizotinib and cabozantinib, identifying a novel therapeutic target for lung adenocarcinoma." (PMID 33772655, 2021). "In a series of lung adenocarcinoma patients metastatic to the spine with mutational data for selected markers (ALK, MET, ROS1, EGFR, and KRAS), the presence of clinically targetable mutations was found to be associated with increased survival." (PMID 40647516, 2025). "We reported a case of initially diagnosed advanced lung adenocarcinoma co-harboring EGFR Ex19del mutation and MET de novo amplifications." (PMID 40034596, 2025). "The stress-induced upregulation of endogenous MET protein was consistently observed in EKVX lung adenocarcinoma cell lines challenged with various stressors." (PMID 39774381, 2025). "Amplifications in 5p15.33 (TERT) and 7q31.2 (MET) have been previously found to characterize lung adenocarcinoma (LUAD) profiles." (PMID 40843133, 2025). "This breakthrough study underscores the efficacy of c-MET-specific CARs in fortifying NK cells against c-MET+ lung adenocarcinoma." (PMID 39664377, 2024). "To further investigate the antitumor efficacy of WntSI in patients with NSCLC, we established a patient‐derived xenograft (PDX) model of lung adenocarcinoma harboring EGFR mutation and MET amplification in NOD/SCID mice." (PMID 38867713, 2024). "In the same way, Schoenfeld and collaborators, in a large cohort of lung adenocarcinoma, found that alterations in KRAS and MET were significantly associated with high expression of PD-L1, whereas EGFR mutations were associated with low PD-L1 levels." (PMID 38611088, 2024).
lung adenocarcinoma (continued). "Here, we report a 50-year-old male patient with EGFR-mutant lung adenocarcinoma and stepwise acquired resistance by a focal amplification of MET followed by D1246N (D1228N), D1246H (D1228H), and L1213V (L1195V) point mutations in MET, all detected by NGS." (PMID 37887535, 2023). "ACTA2 has been reported to promote invasion and metastasis in lung adenocarcinoma by regulating c-MET and FAK expression." (PMID 36768307, 2023). "The PIM1 kinase regulates c-MET expression via phosphorylation of eukaryotic translation initiation factor 4B (eIF4B), thus promoting lung adenocarcinoma proliferation." (PMID 37381723, 2023). "Multiple genetic alterations have been identified as therapeutic targets in lung adenocarcinoma, including mutations in EGFR, ERBB2, BRAF, KRAS, and MET and rearrangements of ALK, RET, and ROS1." (PMID 37628603, 2023). "Subsequent characterization revealed the genomic landscape of these fusions and MET fusion‐positive lung adenocarcinoma cases." (PMID 37326363, 2023). "The MET inhibitors are currently considered as predictive biomarker in patients with lung adenocarcinoma and c-MET has been considered as a potential therapeutic target in OCCC." (PMID 37303048, 2023). "Among these MET aberrations, MET exon 14 skipping is one of the rare mutations in non-small cell lung cancer (NSCLC), accounting for 2–4% of lung adenocarcinoma pathogenesis and progression." (PMID 37400762, 2023). "Recently, NFYC-AS1 (Nuclear transcription factor Y subunit C antisense RNA 1) has also been shown to promote lung adenocarcinoma development through autophagy, apoptosis, and the oncogenic proteins MET/c-Myc38." (PMID 37821547, 2023). "Common driver mutations (EGFR, ALK, BRAF, ERBB2, KRAS, MET, RET, and ROS1) analysis were performed in lung adenocarcinoma tissue samples from two PEAC patients (P08 and P10) using next-generation sequencing." (PMID 35172862, 2022). "CDH1 is a widely known proto oncogene in the occurrence and development of cancer, while a relatively new oncogenic determinant MET regulates the occurrence, progression, and malignancy of epithelial carcinomas including lung adenocarcinoma." (PMID 36138770, 2022). "Herein, based on NGS panel analysis, we firstly described a 61-year-old woman with lung adenocarcinoma who harbored a novel MET exon 14 skipping (c.3004_3028+3del) concurrent MET amplification (copy number: 3.91) and benefited from Savolitinib treatment." (PMID 35444936, 2022). "Our analysis shows frequent mutations and amplifications of MET in TCGA KIRP (kidney renal papillary cell carcinoma) and LUAD (lung adenocarcinoma) cohorts." (PMID 35975235, 2022). "We tested an alternative lung adenocarcinoma cell line, H3122, and inhibiting MET with Crizotinib reduced mature LRP6, an effect that was almost abolished when ZNRF3/RNF43 where siRNA-inhibited." (PMID 34590584, 2021). "Oncogenes were detected in 64% of lung adenocarcinomas, while available information in relation to EGFR, BRAF, KRAS, ALK, ROS1, and MET gene mutations in lung adenocarcinomas are growing steadily." (PMID 34708154, 2021). "In particular, patients diagnosed with lung adenocarcinoma and MET amplification showed acquired resistances when treated with epidermal growth factor receptor (EGFR) inhibitors like Gefitinib or Erlotinib, regardless of EGFR mutation status." (PMID 34733418, 2021). "Statistically, only 4% of lung adenocarcinomas show a MET amplification detected by FISH and are potential candidates for a targeted therapy." (PMID 34733418, 2021). "One cell line in each of the gastrointestinal and lung adenocarcinoma pairs had previously been described as sensitive and the other as resistant to the c-MET inhibitor PHA665752." (PMID 33596971, 2021).
lung adenocarcinoma (continued). "PIM1, in turn, was shown to enhance the growth of lung adenocarcinoma by potentiating the c-MET signaling pathway and the growth of prostate carcinoma and triple-negative breast cancer in cooperation with MYC." (PMID 32504181, 2020). "Intriguingly, it has been seen that driver fusions in lung adenocarcinomas co-occur with SETD2 mutations (16% of cases) in contrast with lung adenocarcinomas with EGFR, KRAS, BRAF and MET mutations, where the frequency of SETD2 mutations is only 2%." (PMID 32516941, 2020). "Recently we have reported that SFN stabilizes receptor tyrosine kinases such as EGFR and MET by facilitating their deubiquitination in lung adenocarcinoma cells." (PMID 30899432, 2019). "One lung adenocarcinoma patient with MET amplification detected by our method reached partial response to crizotinib." (PMID 31739500, 2019). "HGF not only activates the c-MET signaling pathway to induce EGFR-TKIs resistance in lung adenocarcinomas, but it also promotes the transcription of the endogenous c-MET gene." (PMID 31747941, 2019). "The coefficient of correlation (R2) of PD-L1 and c-MET expression in lung adenocarcinoma or the EGFR mutant subgroup was 0.332–0.387 (p < 0.05)." (PMID 31747941, 2019). "Functional studies have demonstrated proliferative potential of FAM83H‐AS1 through MET/EGFR signaling in lung adenocarcinoma and NOTCH1 signaling pathway in colorectal cancer." (PMID 30959550, 2019). "For capmatinib targeting MET in EGFR mutated lung adenocarcinoma with disease progression on EGFR-TKI treatment, gains of ≥ 6 copies have been related to response to combined MET and EGFR targeting." (PMID 30888490, 2019). "This is analogous to adenocarcinoma of the lung where fusion genes involving MET, ROS1, and ALK are all treated with TKIs that are effective against each of the kinase domains." (PMID 29654269, 2018). "Some genes significantly mutated were exclusively mutated in lung adenocarcinoma, such as STK11 (LKB1), RBM10, KEAP1, RIT1 and MET, while other genes such as NFE2L2, KDM6A, RASA1, NOTCH1 and HRAS are significantly mutated in LSQCC." (PMID 30060526, 2018). "MET exon 14-alteration accounted for 0.9–3.0% of lung adenocarcinoma, while c-Met protein was reportedly overexpressed in about 22.2–67.2% of NSCLC and associated with poor prognosis." (PMID 30477470, 2018). "The comparison was carried out by selecting an EGFR-mutant lung adenocarcinoma patient with known drug-resistance mechanisms to EGFR inhibitors via MET amplifications from the TCGA cohort (NSCLC, TCGA-38-4629)." (PMID 29848362, 2018). "The lung adenocarcinoma dataset SRA ERP001058 contains 41 tumors with known targetable or oncogenic mutations in 6 genes: EGFR, KRAS, NRAS, MET, BRAF and CTNNB1." (PMID 30255803, 2018). "The most recent studies have indicated that the MET mutation was not only related to NSCLC but also contributed to the occurrence of pulmonary sarcomatoid carcinomas and lung adenocarcinomas." (PMID 29348894, 2017). "Briefly, among newly detected mutations in lung adenocarcinoma, AKT, BRAF, FGFR2, HRAS, and KIT mutations were detected in one sample (1.3%), MAP2K in two samples (2.6%), MET in 4 samples (5.9%), and FGFR3 in 5 samples (7.4%)." (PMID 28404952, 2017). "In lung adenocarcinoma, MET amplification is significantly associated with IHC3+ MET overexpression." (PMID 29285237, 2017). "We also found that EGFR copy number gain was seen in all lung adenocarcinoma patients whose tumor harbored MET exon 14 skipping in TCGA (The Cancer Genome Atlas) cohort." (PMID 27223439, 2016). "In lung adenocarcinoma tissues, we demonstrated that low expression of miR-206 were also correlated with increased cisplatin resistance and MET expression." (PMID 27014910, 2016).
lung adenocarcinoma (continued). "Ectopic expression of miR-206 mimics inhibited cisplatin resistance, decreased the migration and invasion in cisplatin-resistant lung adenocarcinoma cells, partly due to inactivation of MET/PI3K/AKT/mTOR signaling pathway." (PMID 27527856, 2016). "Lepidic/acinar component were present in 58.8% of invasive lung adenocarcinomas with MET exon 14 skipping." (PMID 27223439, 2016). "Recent genomic studies in lung adenocarcinoma have identified other potential therapeutic targets, such as mutations in KRAS, HER2 and BRAF, ROS1 rearrangements, RET fusions and MET amplification." (PMID 25789627, 2015). "Our results showed that curcumin down-regulated cyclin D1 and c-MET expression in lung adenocarcinoma xenograft tissues." (PMID 21858220, 2011). "In addition, we examined the probability of recurrence-free survival and overall survival in 40 early lung adenocarcinoma patients with KRAS G12C mutation stratified by KRAS and MET mRNA levels." (PMID 38867255, 2024). "However, in a recent study, researchers from Memorial Sloan Kettering Cancer Center reported a case of lung adenocarcinoma with EGFR L858R mutation, where MET gene exon 14 skipping mutation (c.2899G>A) occurred after resistance to erlotinib treatment." (PMID 39582541, 2024). "Moreover, several other oncogenes with potential prognostic roles in lung adenocarcinoma, including MET and PIK3CA, have also been described." (PMID 37628603, 2023). "In addition, we detected the synergistic effect of gefitinib and BYL719 in organoids derived from a lung adenocarcinoma patient, harboring EGFR (L838V, L861Q), PIK3CA (H1047L), ErbB2 (D871N) mutations and MET amplification." (PMID 37553597, 2023). "Moreover, the synergistic effect of gefitinib and BYL719 was also confirmed in the 3D cell culture model, the in vivo model, as well as in the organoid model from a lung adenocarcinoma patient with EGFR, ErbB2, PIK3CA mutations and MET amplification." (PMID 37553597, 2023). "Hence, we reported that a patient with advanced lung adenocarcinoma harboring the EGFR T263P mutation, L858R mutation and MET amplification was resistant to osimertinib but significantly benefited from erlotinib and capmatinib treatment." (PMID 36212397, 2022). "Heterogeneous to the two most common subtypes of lung adenocarcinoma and squamous cell carcinoma in NSCLC, driver mutations, primarily KRAS and MET mutations, may be intrinsic drivers of the malignant features of PSC." (PMID 36341325, 2022). "Mechanistically, FAM83A-AS1 promotes tumor progression and autophagy may through MET-AMPKɑ signaling in lung adenocarcinoma." (PMID 35635086, 2022). "However, c-MET amplification is found in only 5% of patients with newly diagnosed lung adenocarcinoma." (PMID 34490234, 2021). "The reciprocal crosstalk between EGFR and MET in lung adenocarcinoma suggests that simultaneous inhibition through the combined use of EGFR-TKI and MET-TKI would benefit and potentially improve the survival outcomes of patients with concurrent EGFR and MET aberrations." (PMID 34660287, 2021). "A 45-year old man with 60 pack-year smoking history (P05) was diagnosed with EGFR L858R-mutant stage IV lung adenocarcinoma and received a combination of osimertinib and crizotinib after acquiring MET amplification with an absolute CN of 4.98 at disease progression from first-line erlotinib therapy." (PMID 34660287, 2021). "To confirm the clinical relevance of this finding, we extracted 740 lung adenocarcinoma from TCGA database, among which 54 patients were confirmed with EGFR activating mutation (n = 25), FGFR1/2 amplification (n = 15), MET amplification (n = 12), or RET fusion (n = 2)." (PMID 31221965, 2019).
lung adenocarcinoma (continued). "As a proof of concept of the clinical relevance of this new mechanism of adaptive resistance, we report that a patient with a MET‐amplified lung adenocarcinoma displayed deregulation of the miR‐205/ERRFI1 axis in concomitance with onset of clinical resistance to anti‐MET therapy." (PMID 30021798, 2018). "At the time of this study, analysis of ALK, ROS and MET mutations were not part of the standard of care in lung adenocarcinoma." (PMID 30064401, 2018). "For example, in lung adenocarcinomas, gene-expression profiles from tumors with somatic aberrations in EGFR or MET were negatively correlated with each other, in line with prior knowledge that MET amplification causes resistance to EGFR inhibition." (PMID 29322935, 2017). "Recent data showed that a MET/CEP7 ratio >5 was able to discriminate lung adenocarcinoma with no other driver mutations and was associated with high objective response rate to crizotinib." (PMID 29285237, 2017). "We explored this hypothesis by evaluating the response of three lung adenocarcinoma cell lines that differ only in their EGFR genotype to the MET inhibitor SGX523 in vitro and in a murine xenograft model derived from the same cells." (PMID 28141869, 2017). "A MET mutation causing exon 14 skipping in RJLC2-T3 (c-METΔE14), and ARAFS214C, identified in RJLC3-T2, have been recently reported to be oncogenic in preclinical models and lung adenocarcinoma patients." (PMID 29018192, 2017). "In the current study, we demonstrated that miR-206 could suppress EMT process and cisplatin resistance of lung adenocarcinoma cells, partly through targeting MET and its downstream PI3K/AKT/ mTOR pathway both in vitro and in vivo." (PMID 27014910, 2016). "Pre-gefitinib MET FISH status may be useful for predicting PFS and OS after Gefitinib treatment in lung adenocarcinoma with EGFR mutation and for selecting the patients who would benefit from EGFR-TKI and MET inhibitor therapy." (PMID 25886066, 2015). "MET was found overexpressed in up to 67% of lung adenocarcinomas in our previous study." (PMID 19238632, 2008). "Therefore, in this study, we aimed to analyze the treatment efficacies and toxicities of combination therapy in patients with advanced EGFR-mutant lung adenocarcinoma (LUAD) with MET overexpression after progression from EGFR TKI treatment in the real-world setting." (PMID 40470164, 2025). "S49076 could exert its cytotoxic action at low doses on Met-dependent cells, GTL16 and U87-MG, via MET inhibition, whereas it restrained the growth of MET-independent lung adenocarcinoma cells H441, H460, and A549 at higher but clinically relevant doses by targeting AURKB." (PMID 33202573, 2020). "Semaphorin or juxtamembrane mutations may not lead to MET activation, while splice site mutations seen in 4% of lung adenocarcinomas and 2% of squamous cases may lead to MET activation via exon 14 skipping in MET mRNA with response to MET inhibitors." (PMID 29050231, 2017). "Aberrant MET activation can be caused by several altered biological processes, but mainly two are of clinical interest in NSCLC: MET gene amplification, which is observed in 2%–4% of NSCLC, and MET exon 14 skip mutations, which have been found in 3%–4% of lung adenocarcinomas." (PMID 29225694, 2017). "Inflammatory cancer-associated fibroblasts have been shown to promote NSCLC brain metastasis through the MET-HGF pathway, and fibroblasts interact with endothelial cells to promote angiogenesis in lung adenocarcinoma brain metastases." (PMID 39400127, 2024). "Recent Asian expert consensus has reported that the percentage of EGFR alterations in lung adenocarcinoma is higher among East Asian compared to Western population (40–55% vs. 12–25%), while KRAS, BRAF, and ROS1 are lower, with HER2 and MET are nearly similar." (PMID 38245692, 2024).